IL24 (interleukin 24)
Diseases named in the same sentence as IL24 in open-access papers (continued):
Sharing a sentence is not in itself a finding about the gene and the disease.
tumor (continued). "The anti-tumor efficacy of these engineered exosomes with NKG2D and IL24 was confirmed across a range of cancer cells, providing a novel approach for targeted cancer therapy." (PMID 40076725, 2025). "In clinical samples analysed by TCGA, the expression of 5 genes, CCL20, IL1B, IL24, PLAU and SEMA7A, was significantly higher in the primary tumour than in solid normal tissue, whereas that of CITED2 was lower." (PMID 38363001, 2024). "In MLS, IL-24 expression is decreased, and knockdown of FUS::DDIT3 results in increased IL-24 expression and inhibition of tumor cell growth." (PMID 39456230, 2024). "Several tumor suppressor genes are in this part of chromosome 1, including HRPT2, MDA7/IL-24, IFI16, and thus promoting tumor proliferation and growth." (PMID 36830839, 2023). "In addition, treatment of the 143B OS mouse model with IL‐24 revealed inhibition of the tumor growth rate and downregulation of Notch 1, Hes 1, and β‐catenin expression in xenograft tumor tissues, suggesting that IL‐24 may be a new target to improve long‐term survival of patients with OS." (PMID 37441462, 2023). "Some examples are reported in several studies that have demonstrated the release of chemokines and cytokines such as CCL21; IL-2; IL-4; IL-18; IL-24; IFN-γ; and LIGHT, also known as a lymphotoxin analogue, into the tumor microenvironment." (PMID 36077761, 2022). "A higher tumor growth inhibition was observed in B. breve-IL24 compared with B. breve-GFP group and higher tumor growth inhibition in B. breve-GFP compared with the Saline group." (PMID 35814447, 2022). "For this purpose, tumor-bearing mice received either E7 DNA vaccine, MDA-7/IL-24 cytokine or combination of E7 vaccine with MDA-7/IL-24 adjuvant one week after tumor challenge and boosted two times with one-week interval." (PMID 35752792, 2022). "In tumor cells, apoptosis is induced independently of the JAK/STAT pathway after the exogenous addition of IL-24." (PMID 35884907, 2022). "Compatible with our immunological data, a high synergism in eliciting the cytolytic action of cytotoxic T lymphocytes, along with tumor destructive and IFN-γ-releasing cells was detected in the adjuvant E7&IL-24 group when compared to IL-24 or even E7 group." (PMID 35752792, 2022). "The combined administration of secretable grp170 and MDA-7/IL-24 significantly enhanced the antigen-specific CD8 + T-cell frequency and tumor-specific cytolytic activity, which was further supported by an in vivo antibody depletion study." (PMID 35008495, 2021). "In tumor bearing mice CCL24, CD163 and MMP7 were upregulated after therapy and IL24 and Odc1 were downregulated (p > 0.05)." (PMID 34944584, 2021). "Based on our tumor-targeting replicative viral vector ZD55, we constructed ZD55-IL-24 by inserting the exogenous antitumor gene mda-7/interleukin-24 (IL-24) gene into the cloning site of ZD55." (PMID 33903973, 2021). "More importantly, IL-24 transformed the TME and enhanced anti-tumor effects in favor of tumor elimination." (PMID 33419310, 2020). "Low concentration of IL-24 inhibited CD4+ T cell proliferation and dampened tumor-infiltrating Th1 response." (PMID 31921658, 2019). "In order to improve the antitumor activity induced by Newcastle disease virus (NDV)-modified tumor vaccine, we generated a recombinant NDV expressing IL-24 using reverse genetics." (PMID 31338417, 2019). "To determine the effect of the tumor suppressor IL-24 on the expression of SHH signaling components, we used the H1299 cell line (labeled ‘H1299-IL24’), which was stably transfected with doxycycline-inducible plasmid vector (pTET-IL-24)." (PMID 31783569, 2019). "LX/IL-24-infected tumor cells increased infiltration of CD4+ T cells and CD8+ T cells in tumor sites, and the antitumor activity of the tumor vaccine modified with LX/IL-24 was dependent on CD8+ T cells." (PMID 31338417, 2019).
tumor (continued). "One hundred Nanograms per milliliter of IL-24 stimulation enhanced IFN-γ expression in both peripheral and tumor-infiltrating CD4+ T cells (Dunn's multiple comparison tests, P < 0.0001)." (PMID 31921658, 2019). "They investigated the combined therapy with IL-24 and the tumor necrosis factor-related apoptosis-inducing ligand (TRAIL), which was considered as a promising anti-tumor agent expressed in two Ads, respectively." (PMID 31781493, 2019). "The combination treatment of IL-24 and HMGA1 siRNA showed the highest inhibition of tumor cell migration (p<0.001) and invasion (p<0.001), compared with all other treatments." (PMID 27602961, 2016). "The apoptotic activity detected in other treated groups was much lower than in the MSC.LentiR.E1A+Ad-hTERTp-IL24 plus 5-Fu group, indicating that MSC.LentiR.E1A+Ad-hTERTp-IL24 and 5-Fu were synergistically induced tumor cell death in vivo." (PMID 27322080, 2016). "Our identification here of the MDA-7/IL-24 target PERP, another member of the GAS-3/PMP-22 family with strong tumor inhibitory activity, further highlights the importance of this gene family in malignant transformation." (PMID 26460950, 2015). "A type 5 adenovirus (Ad5) was engineered to specifically replicate in tumor cells by expressing Ad5-E1A under the control of a cancer-specific promoter derived from progression elevated gene-3 and also produces MDA-7/IL-24 (Ad5-CTV)." (PMID 26474456, 2015). "The immune system plays a very important role in regulating tumor growth and progression and hence understanding the role of MDA-7/IL-24 in immune competent mice is important." (PMID 26474456, 2015). "Results from the clinical trial showed intratumoral administration of Ad-IL24 (INGN 241) resulted in tumor cell apoptosis both at the treated site and in tumor cells at a distant site." (PMID 24377906, 2013). "Molecular studies showed both Ad-IL24 and Bevacizumab treatment reduced VEGF expression levels in tumor cells both in vitro and in vivo." (PMID 24377906, 2013). "The percent positive cells for VEGF expression was significantlyreduced by the three treatments (IL-24, IFN-α, and the combined therapy).These data indicated that the combined therapy mediated its anti-tumor activityvia multiple pathways." (PMID 22569271, 2012). "The effects of extracellular MDA-7/IL-24 are mediated by binding to IL-20Rα/β receptors on tumors cells, inducing modulation of the ERK, JNK, MAPK pathways to induce anti-tumor effects." (PMID 22808125, 2012). "IL24 is a member of the IL10 cytokine family and has been shown to selectively induce apoptosis in tumor cells without affecting normal cells, and it is known for its bystander effects, inducing apoptosis in neighboring tumor cells as well." (PMID 40076725, 2025). "Our findings revealed that some CAF subclusters were simultaneously enriched in metastatic lymph nodes and primary tumor sites, such as mCAF1 (MMP3+IL24+) and mCAF4, suggesting that these subclusters may serve as key roles in facilitating metastasis in ESCC." (PMID 39741182, 2025). "We also found that HMGB1, a TLR4 agonist that can induce IL-24, is highly upregulated in calcipotriol-treated tumor cells in a CD4+ T cell–dependent manner, suggesting that it may contribute to IL-24 induction in macrophages." (PMID 39782693, 2025). "Furthermore, stromal cells in the tumor microenvironment, including MMP3+IL24+ fibroblasts, APLN+ endothelial cells, and CXCL12+ pericytes, were implicated in ESCC metastasis through angiogenesis, collagen production, and inflammatory responses." (PMID 39741182, 2025). "Notably, the combination of NKG2D and IL24 had a more pronounced effect on A549 and HELA cells over time, highlighting the potential of this strategy in targeting different tumor types." (PMID 40076725, 2025). "Importantly, IL-24 also showed therapeutic potential in vivo, where adenoviral delivery significantly inhibited ARMS tumor growth." (PMID 40508013, 2025).
tumor (continued). "In addition, IL-24 activates STAT3, which often predicts tumor progression, and VG9-IL-24 can counteract the tendency of STAT3 phosphorylation." (PMID 40469178, 2025). "As tumor cells such as A549, HELA, and MCF-7 frequently overexpress these ligands, the augmented targeting ability of IL24/NKG2D-co-expressing exosomes could contribute to more effective tumor cell killing." (PMID 40076725, 2025). "At high concentrations, IL-24 activates the proteins PERK and eIF2, leading to reduced expression of survival proteins and simultaneously activating a ceramide-dependent pathway that induces apoptosis in tumor cells." (PMID 40607413, 2025). "OSU‐03012 enhanced the IL‐24‐mediated cytotoxicity in GBM cell lines; the combination increased PKR‐PERK while reducing the expression of the anti‐apoptotic proteins MCL‐1 and BCL‐XL, resulting in a profound anti‐tumor effect." (PMID 40338095, 2025). "The dual targeting of tumor cells via NKG2D engagement and IL24-induced apoptosis could potentially overcome the limitations of conventional therapies, such as drug resistance and off-target toxicity." (PMID 40076725, 2025). "Further tumor tissue analysis revealed that B. breve-IL24 treatment led to decreased expression of the anti-apoptotic protein BCL-2 and increased expression of the pro-apoptotic protein Bim, supporting its role in promoting tumor cell apoptosis." (PMID 40805186, 2025). "NK-Exo, when engineered with both IL24 and NKG2D, exhibit enhanced tumor selectivity and killability due to the tumor-specific properties of IL24 and the ability of NKG2D to target highly overexpressed ligands on tumor cells, making NK-Exos a more effective and safer therapeutic alternative." (PMID 40076725, 2025). "In line with the proposed mechanism, immunofluorescence analysis demonstrated a marked upregulation of ATF3 expression in tumor tissues from Vin-treated mice, supporting the in vivo activation of the P38/MAPK/ATF3 signaling pathway and its role in mediating IL-24 expression." (PMID 40866941, 2025). "Additionally, vinburnine activates the P38/MAPK/ATF3 signaling axis, which drives the secretion of interleukin-24 (IL-24), enhancing the functionality of CD8+ T cells and modulating the tumor immune microenvironment to favor antitumor immunity." (PMID 40866941, 2025). "Moreover, there are reports indicating that IL‐24 is involved in modulating EMT, a process known to promote tumor cell invasion and confer resistance to anti‐cancer therapies." (PMID 40338095, 2025). "In addition, OVs carrying TRAIL and cytokines, such as IL-12 and IL-24, have also been studied in HCC, and these genes makes the recombinant virus have an impact on tumor immunity while inducing cell apoptosis." (PMID 37182136, 2023). "Several studies provide compelling evidence that MSCs can be genetically engineered to deliver anti-tumor drugs (PTX, DOX) and immunomodulatory factors (IL-12, IL-24, IFN-Υ, IFN-β, TRAIL, PEDF, apotin, CDA/UPRT and CX3CL1) to target cells, thereby conferring anti-tumor/anti-metastatic actions." (PMID 36739406, 2023). "In addition, they reported the effects of IL-24 on the signaling pathways of ERK-1/2, AKT, and JNK, as well as its ability to inhibit both tumor angiogenesis in vitro and in vivo and the tumor growth of tumor-bearing mice." (PMID 36742134, 2023). "Interleukin-24 (IL-24) has specific inhibitory effects on the proliferation of various tumor cells with almost no toxicity to normal cells." (PMID 36282328, 2022). "Measurements in the 4th week revealed that although the difference between the tumor volume of E7&IL-24 and E7 groups was not noticeable, a smaller (P < 0.001) tumor was observed in both groups compared to the IL-24 group." (PMID 35752792, 2022).
tumor (continued). "Therefore, in the current study, we evaluated whether MDA-7/IL-24 could be a candidate vaccine adjuvant to induce antigen-specific cellular immunity and enhance antitumor immune responses in a mouse model of the HPV-associated tumor when combined with an E7 DNA vaccine." (PMID 35752792, 2022). "The overexpression of IL-24 was found to inhibit VEGF in Ishikawa cells and xenograft tumor." (PMID 36531027, 2022). "But NaBu treatment can affect several tumor and immune-related pathways in FCHO/IL-24 cells, which may indirectly stimulate the secretion of rhIL-24 protein." (PMID 36282328, 2022). "The therapeutic gene engineered here was interleukin-24 (IL-24), which is a novel tumor suppressor cytokine that induces apoptosis in various tumor cells but has no significant cytotoxicity to normal cells." (PMID 35292065, 2022). "IL24 is a pleiotropic immune cytokine in the IL10 family, as well as a broad-spectrum tumor suppressor, which can induce apoptosis, inhibit angiogenesis, block metastasis and increase the sensitivity of radiotherapy and chemotherapy without affecting the normal cells." (PMID 34955744, 2021). "Previous study showed that oncolytic adenovirus ZD55-IL-24 with the deletion of E1B-55 gene and the insertion of IL-24 gene, had a better anti-tumor effect than ZD55 with no toxicity to normal cells." (PMID 32318337, 2020). "Our previous studies showed that ZD55-IL-24, an oncolytic adenovirus harboring IL-24, had better anti-tumor effect with no toxicity to normal cells." (PMID 32318337, 2020). "Our previous studies have shown that ZD55-IL-24 could selectively replicate in many types of human tumor cells and kill these cells much more effectively than ONYX-015 or the replication-defective adenovirus carrying the IL-24 gene both in vitro and in vivo." (PMID 33257647, 2020). "The sROC curve showed the AUC of OSCC was 0.94, while the AUC of LSCC was 0.86, which both suggested the IL24 mRNA had the ability to distinguish between tumor tissues and noncancer tissues." (PMID 33014054, 2020). "LX/IL-24-infected tumor cells constantly expressed IL-24, while LX/RFP-infected tumor cells did not produce detectable IL-24." (PMID 31338417, 2019). "Low concentration of IL-24 did not affect T-bet mRNA relative level in either peripheral or tumor-infiltrating CD4+ T cells (Tukey tests, P > 0.05)." (PMID 31921658, 2019). "Similarly, IL-24 mRNA expression in tumor-infiltrating CD4+ and CD8+ T cells was also remarkably reduced when compared with those from non-tumor tissue (Mann-Whitney tests, all P < 0.0001)." (PMID 31921658, 2019). "Our results demonstrate that IL-24, but not IL-22, is required for the skin reaction induced by PPD application." (PMID 30755657, 2019). "Low concentration of IL-24 stimulation did not affect the peripheral Th1 percentage (Tukey test, P = 0.642), however, significantly down-regulated tumor-infiltrating Th1 percentage (1.30 ± 0.19% vs. 1.67 ± 0.28%, Tukey test, P < 0.0001)." (PMID 31921658, 2019). "Interleukin-24 was originally identified in healthy melanocytes abut not metastatic melanoma cells and was considered to be a mediator of tumor suppression." (PMID 29681905, 2018). "Augmented killing efficacy of IL-24 in synergy with various anticancer approaches such as chemotherapy, radiation, and monoclonal antibodies has been demonstrated in a broad range of tumor cells without harming normal cells." (PMID 27203744, 2016). "In the MSC.LentiR.E1A+AdTrack group, GFP-expressing tumor cells lacking IL-24 expression were observed as expected." (PMID 27322080, 2016). "Tumors treated with MSC.LentiR.E1A+Ad-hTERTp-IL24 with or without 5-Fu presented significantly apoptosis, which was limited to the tumor mass." (PMID 27322080, 2016). "Secreted IL-24 protein, generated from Ad.IL-24-infected cells, exerts anti-angiogenic activity by inhibiting endothelial cell differentiation and by blocking the activities of VEGF and TGF-α via inhibition of Src activity within tumor cells." (PMID 27271601, 2016).
tumor (continued). "Compared with the no treatment groups, Ad-hTERTp-IL24 and LentiR.E1A co-loaded HUMSCs exhibited significant anti-tumor activity in vivo, particularly in combination with low doses of 5-Fu." (PMID 27322080, 2016). "Nevertheless it is evident that HMGA1 expression was higher in tumor tissues compared to normal while IL-24 was not detectable in tumor tissues independent of histology." (PMID 27602961, 2016). "While mda-7/IL-24 is being developed as a cancer therapeutic, the molecular mechanisms by which it exerts it anti-tumor and anti-metastatic activities are not completely understood." (PMID 25775124, 2015). "Correlating with the tumor cell migration study results, CXCR4, pAKTS473 and pPRAS40T246 protein expression were all reduced in the cells that were treated with AMD3100 alone, IL-24 alone, and AMD3100 plus IL-24 when compared to control cells (P<0.05)." (PMID 25775124, 2015). "As a control, we included Ad5-E1A that also replicates in tumor cells, but lacks MDA-7/IL-24." (PMID 26474456, 2015). "IL-24 secreted by adjacent tumor or normal cells can induce direct antitumor effect in tumor cells not initially receiving this gene product." (PMID 26361755, 2015). "MMP1, IL24 and CCL20 are mRNAs that are well studied for their role in cancer; however the remaining mRNAs have not been characterized for their potential role in HNSCC tumorigenesis and/or tumor progression and warrant further study." (PMID 26498364, 2015). "Tumor cells or normal cells infected with AdLTR2EF1α-IL-24 inhibit the surrounding tumor cells, that not initially infected with AdLTR2EF1α-IL-24, through the “bystander” effect." (PMID 26361755, 2015). "Paradoxically, IL24 mRNA is up regulated in HNSCC tumor samples in comparison to normal tissues according to the 541 patient TCGA HNSCC dataset, this suggests that IL24 may promote HNSCC tumorigenesis and/or tumor progression." (PMID 26498364, 2015). "To evaluate whether IL-24 mediates its anti-tumor function by inhibiting AKT activation and phosphorylation is required for AKT inhibition, we knocked down AKT in H1299-IL-24 cells with si-AKT." (PMID 26009991, 2015). "Finally, IL-24 when combined with CXCR4 inhibitors (AMD3100, SJA5) or with CXCR4 siRNA demonstrated enhanced inhibitory activity on tumor cell migration." (PMID 25775124, 2015). "Since CXCR4 has been shown to play a role in tumor metastasis by promoting cell migration and invasion we investigated whether the attenuation of CXCR4 expression by IL-24 had a consequential biological effect." (PMID 25775124, 2015). "We demonstrated for the first time that lack of IL-24 phosphorylation affects its subcellular localization, secretion, and anti-tumor activity." (PMID 26009991, 2015). "When tumor sections were assessed for MDA-7/IL-24 expression by immunohistochemistry, we observed that both injected and uninjected tumors in the mice showed the presence of MDA-7/IL-24." (PMID 26474456, 2015). "Follow-up studies by the same group investigated whether protein-protein interaction between IL-24 and PKR was important for tumor cell killing." (PMID 24377906, 2013). "It is evident from these reports that IL-24 selectively induces ROS-mediated cell death in tumor cells but not in normal cells." (PMID 24377906, 2013). "Furthermore, combining radiation therapy with Ad-IL24 resulted in greater inhibition of VEGF, bFGF, IL-8 and tumor neovascularization resulting in enhanced antitumor activity." (PMID 24377906, 2013). "Apart from having a significant reduction in the tumor growth treated with Ad.MDA-7, inhibition of the contralateral tumor that was not treated with Ad.MDA-7 was observed demonstrating the ‘bystander’ tumor killing activity for IL-24 protein." (PMID 24377906, 2013). "Their study unveiled a new observation showing IL-24 physically bound the double stranded RNA-dependent protein kinase (PKR) protein and its binding resulted in phosphorylation of both proteins that contributed to tumor cell killing." (PMID 24377906, 2013).